TLR4 (toll like receptor 4)
Diseases named in the same sentence as TLR4 in open-access papers (continued):
Sharing a sentence is not in itself a finding about the gene and the disease.
Stroke (continued). "In this study, we demonstrated that the expression of and TLR4, similar to IBA1, was significantly increased on day 5 in stroke brain." (PMID 26186541, 2015). "In the context of an experimental pre-conditioning event, systemic application of LPS, Pam3CysSK4, or CpG ODN, activating TLR4, TLR2, and TLR9, respectively, prior to an experimental stroke results in protection of the mouse brain." (PMID 25239168, 2014). "The authors thought that the therapy with VELCADE and tPA abolished the inactivation of fibrin/fibrinogen on NF-κB by directly inhibiting stroke-activated TLR2, TLR4, and IRAK1 and suppressing inflammatory respond." (PMID 23864765, 2013). "Studies that have utilized mice which lack either TLR2 or TLR4 suggest that, following an experimental stroke, increased TLR2 signaling enhances resistance to ischemic brain damage, whereas TLR4 activation aggravates the injurious effects of cerebral ischemia." (PMID 23251498, 2012). "In terms of key signaling pathways, based on analysis of the tectoridin-stroke PPI network, GO and the KEGG pathway enrichment analysis suggested that PI3K/Akt, Nrf2/HO-1, and TLR4/MyD88/NF-κB play an important role in the therapeutic actions of tectoridin for the treatment of stroke." (PMID 40003867, 2025). "They discovered that cerebral cortical neurons expressed TLR2 and TLR4 in response to ischemia‐reperfusion injury, and that mice lacking TLR2 or TLR4 had considerably less brain damage and neurological abnormalities following a stroke than did WT control mice." (PMID 40165524, 2025). "In young mice, Hdac7 mRNA expression was significantly decreased in the ipsilateral region following photothrombotic stroke, and its expression showed a strong negative correlation with Tlr4." (PMID 40867143, 2025). "Following stroke or central nervous system (CNS) injury, activated microglia express high levels of MD2, which facilitates the recognition of DAMPs, leading to the activation of TLR4 signaling." (PMID 40723833, 2025). "Furthermore, neutrophil extracellular traps (NETs) activated by TLR2 and TLR4 have been shown to worsen colon tissue damage and promote thrombotic events with active inflammatory bowel disease (IBD), resulting in stroke and VD." (PMID 38736878, 2024). "Although the ligand to TLR4 in ischemic stroke is not as well-established as in hemorrhagic stroke, conditional and whole body knockouts of TLR4 in all models of stroke have demonstrated profoundly neuroprotective effects." (PMID 38304427, 2024). "TLR4 was shown to play an important role in neurogenesis by promoting neuroblast migration and increasing the number of new cortical neurons after stroke, despite its negative effect on proliferation in the subventricular zone." (PMID 38891900, 2024). "The TLR4/NF-κB pathway was not as functional as in the stroke model without BM-MSCs+ miR-185-5p application." (PMID 36671691, 2023). "Moreover, the effect of circTTC3 on stroke and NSC biology has been confirmed to be mediated through the miR-372-3p/TLR4 axis." (PMID 36671403, 2022). "As previously stated, the absence of TLR4 mediates a neuroprotective effect due to the inhibition of the inflammatory response after stroke." (PMID 34745132, 2021). "Several studies have proven that the lack of TLR4 entitles improved neurological and behavioral outcomes in different animal models of experimental stroke." (PMID 34745132, 2021). "By selectively targeting neutrophil TLR4, it would be possible to block the damaging activity of neutrophils without interfering with the other beneficial roles of TLR4 signaling after stroke." (PMID 34745132, 2021). "Chimeric mice with bone marrow lacking TLR4 showed a reduced infarct volume and edema after experimental stroke indicating that peripheral cells have an important role in stroke pathophysiology." (PMID 34745132, 2021).
Stroke (continued). "Among these molecules, high mobility group box 1 (HMGB1) protein appears in the early stages of stroke and is recognized by several toll-like receptors (TLRs) like TLR2 or TLR4, which trigger an inflammatory response through the release of pro-inflammatory cytokines in an NF-κB-dependent process." (PMID 34208834, 2021). "In order to assess the role of the neutrophilic TLR4 after stroke, mice that do not express TLR4 in myeloid cells (TLR4loxP/Lyz-cre) and its respective controls (TLR4loxP/loxP) were used." (PMID 34745132, 2021). "TLR4-lacking neutrophils showed a higher phagocytic activity in the basal state, they were preferentially engulfed by the microglia after stroke, and they produced less radical oxygen species (ROS) in the first stage of the inflammatory process." (PMID 34745132, 2021). "For instance, lack of TLR4 can protect mice from ischemic brain injury, brain damage/inflammation after experimental stroke, neuroinflammation, brain injury, Parkinson’s disease and demyelination associated with alcohol abuse." (PMID 32780740, 2020). "TLR4 pathways induce the production of reactive oxygen/nitrogen species and oxidative/nitrosative stress, leading to TLR-related diseases, including nephropathy, asthma, arteriosclerosis, stroke, type 2 diabetes, rheumatoid arthritis, and so on." (PMID 30459606, 2018). "Combined with the important role of Inflammation and oxidative stress in stroke, we hypothesized that the combined use of Danshensu and HSYA may significantly increase the therapeutic effect on stroke through TLR4/NF-κB and Nrf2/HO-1 pathways." (PMID 29383171, 2017). "Evaluation of potential long-term adverse effects of anti-TLR4-mAb-treament revealed no significant deleterious effect on infarct volumes nor neurological deficit after 14d of reperfusion in a mild model of stroke (15min MCAO)." (PMID 26849209, 2016). "Despite a negative effect on SVZ cell proliferation, TLR4 plays an important role in stroke-induced neurogenesis by promoting neuroblasts migration and increasing the number of new cortical neurons after stroke." (PMID 25972779, 2015). "However, stroke volumes were not significantly affected by histones infusion in TLR2 KO nor TLR4 KO mice." (PMID 39201339, 2024). "Recently, it has been reported that Toll-like receptor four (TLR4) promotes the phosphorylation of DRP2 via activation of Rho-kinase two in MCAO rats, suggesting that this mechanism may mediate the pathological outcome of TLR4 in stroke." (PMID 37175950, 2023). "In this study, we report for the first time that stroke in T2DM mice induces earlier and higher inflammatory factor, cytokine, and acute phase response protein expression such as SAA, NLRP3, IL-1β, IL-6, TNFα, and TLR4 in the liver compared to heart and kidney." (PMID 36968490, 2023). "Stroke can lead to increased abundance of Gram-negative Enterobacteriaceae bacteria and further increased circulatory LPS levels, which can trigger inflammation via TLR-4 and alter intestinal mucosal ligand protein expression levels leading to a leaky gut." (PMID 35614480, 2022). "For instance, gram negative bacteria in gut can activate TLR-4 in brain endothelial cells, thereafter drives cerebral cavernous malformations via TLR4-MEKK3-KLF2/4 pathway and significantly increases the occurrence and recurrence risk of stroke." (PMID 34712621, 2021). "However, when combined with TLR4 deletion, depletion of neutrophils not only does not induce neuroprotection but also exacerbates brain injury after stroke." (PMID 34335600, 2021). "In summary, the NETosis process seems unlikely to be involved in the neuroprotective effect that neutrophils without TLR4 show in stroke, but we could hypothesize that reduced NETosis due to previous phagocytic activity might mitigate this damaging function." (PMID 34745132, 2021).
Stroke (continued). "Considering that TLR4-lacking neutrophils are, at least, partially responsible for the neuroprotection observed in TLR4loxP/Lyz-cre mice, we decided to globally assess the functionality of the TLR4-lacking neutrophil, and how this affected the outcome after stroke." (PMID 34745132, 2021). "Our data suggest that, after stroke, there is an increase in the production of ROS, which is decreased in neutrophils lacking TLR4, an effect which could mitigate that damage and therefore contribute to neuroprotection." (PMID 34745132, 2021). "However, TLR4 signaling in astrocytes, a ubiquitous cell type involved in the CNS response to injury, and in reparative processes during the chronic phase of stroke, has not been extensively studied." (PMID 32148958, 2020). "According to the results, TLR4, TLR7, and TLR8 are all involved in stroke, in which TLR4 and TLR8 have detrimental roles in ischemic stroke, while the activation of TLR7 can induce robust neuroprotection against stroke by triggering a novel type I interferon-mediated mechanism." (PMID 32565722, 2020). "To test whether naloxone enantiomers affect cytokine secretion, we isolated CD11b+ microglia/macrophages from the infarct area at day 7 post-stroke and measured the secretion of TNF-α, a cytokine with well-characterized pro-inflammatory effects downstream of TLR4 signaling." (PMID 29766045, 2018). "Moreover, our results demonstrate that inhibition of the innate immune receptor TLR4 also alters post-stroke adaptive immune responses in both ischemic and non-ischemic brain tissue." (PMID 26849209, 2016). "Here, we show that the increased expression levels of TLR2, TLR4 and TLR8, adaptor protein MyD88, signalling protein TRAF6, TLR downstream signalling proteins such as NF-κB and MAPKs were significantly prevented in IVIg-treated animals compared to control animals following stroke." (PMID 25886362, 2015). "In this study we show that the absence of TLR4 modifies the neutrophil dynamics and alter their ability to phagocyte and to produces ROS, effects that could contribute to the neuroprotection after stroke." (PMID 34745132, 2021). "Thus, we explored whether LPS (Lipopolysaccharide) or LTA (Lipoteichoic acid) levels are elevated in different causes of stroke and correlated with CRP levels since TLR4 is the receptor for Gram-negative bacterial LPS and TLR2 is the receptor for Gram-positive bacterial LTA, respectively." (PMID 33753837, 2021). "Along with TLR2 and TLR4, increased TLR7 and TLR8 also has been noticed in blood samples of deteriorating stroke patients, but no role has been reported for TLR3 or TLR9 in ischemic injury." (PMID 31134076, 2019). "Studies of stroke using animal models suggest that activation of TLRs by the release of endogenous ligands contributes to tissue injury and indicates that TLR2 and TLR4, but not TLR3, contribute to this pathological process." (PMID 23589665, 2013). "In our study, we did not observe a major involvement of TLR-4 and its downstream Traf6 signaling suggesting that CD8 could be a major upstream activator of mTOR/NF-κB in stroke." (PMID 29342151, 2018). "Preconditioning with low doses of ligands for TLR2, TLR4, and TLR9 all successfully reduce infarct size in experimental models of stroke, including a recent study showing that a TLR9 ligand is neuroprotective in a nonhuman primate model of stroke." (PMID 21999375, 2011).
asthma (198 papers, 2005 to 2026). "The primary objective of this study was to evaluate the association between TLR4 polymorphisms, residential environment, and asthma risk." (PMID 40761635, 2025). "Genetic polymorphisms in the TLR4 gene, particularly rs4986790 and rs4986791, have been studied for their potential roles in modulating asthma susceptibility." (PMID 40761635, 2025). "Recent systems biology analyses identified four potential molecular triggers—AKT1, MAPK13, STAT1, and TLR4—as candidate regulators of asthma-associated signaling pathways." (PMID 40650018, 2025). "TLR4 rs4986791 was found to be significantly associated with asthma susceptibility in a meta-analysis, especially in the Asian population." (PMID 40672946, 2025). "The mechanisms underlying asthma susceptibility in the presence of TLR4 polymorphisms (Asp299Gly and Thr399Ile) have been linked to heightened responsiveness to LPS, a microbial component commonly found in farming and rural environments." (PMID 40761635, 2025). "Numerous authors have linked TLR4 to allergic sensitization and asthma, both by promoting and reducing the inflammatory response, and its increase in the airways of asthmatic patients has been linked to a worse prognosis." (PMID 40650018, 2025). "LPS recognition by TLR4 triggers downstream signaling, leading to the release of Th2 cytokines, which are implicated in asthma pathogenesis." (PMID 40761635, 2025). "The main aim of this study was to identify interactions between two single nucleotide polymorphisms (SNPs) within the TLR4 gene, Asp299Gly and Thr399Ile, and residential area (urban or rural) in females and males with asthma and different asthma phenotypes." (PMID 40761635, 2025). "This study aimed to explore the influence of MUC1 on neutrophil airway inflammation in patients with asthma and verify the underlying mechanism associated with the TLR4/MyD88/NF-κB pathway and NLRP3 inflammasome-mediated pyroptosis." (PMID 37880668, 2023). "This study explored the inhibitory effect of MUC1 on NLRP3 inflammasome-mediated pyroptosis in patients with asthma and revealed that one of the underlying mechanisms is the downregulation of TLR4/MyD88/NF-κB pathway activation." (PMID 37880668, 2023). "Amygdalin attenuated airway epithelial cell apoptosis, inflammation, and epithelial-mesenchymal transition by inhibiting the TLR4/NF-κB signaling pathway in cough variant asthma." (PMID 37559205, 2023). "S100A8/A9 is involved in innate immune responses in Baker’s asthma pathogenesis and is regulated by TLR4 polymorphisms." (PMID 37110453, 2023). "Lately, although contradictory observations have also been published, TLR-4 polymorphisms have been reported to associate with atopy and asthma." (PMID 38045687, 2023). "rs3804099 in TLR2 and rs4986791 in TLR4 are significantly associated with an increased risk of asthma." (PMID 35911120, 2022). "Nonetheless, the mechanism underlying TLR4/MyD88/NF-κB activation in asthma remains to be further explored." (PMID 35156897, 2022). "Previous research has shown that TLR4-mediated inflammation is associated with asthma’s pathogenesis." (PMID 35156897, 2022). "Individuals carrying the Asp299Gly TLR4 polymorphism that were colonized with Mcat at 2 months or H. influenzae at 13 months of age were at an increased risk of asthma development." (PMID 35386999, 2021). "The aim of this study was to explore the possible role of TLR4 polymorphisms in the development of childhood asthma." (PMID 32650475, 2020). "From a clinical point of view, it would be important to study the effect of TLR4 polymorphism on the severity of asthma and responsiveness to medication in the future." (PMID 32650475, 2020). "It has been reported that two TLR2 single-nucleotide polymorphisms (SNPs) and four TLR4 SNPs significantly modified the effect of air pollution on the prevalence of doctor-diagnosed asthma from birth up to 8 years of age." (PMID 32411804, 2020).
asthma (continued). "In line with the association between TLR4 SNPs and asthma after bronchiolitis, infants with Asp299Gly and/or Thre399Ile in TLR4 experience a skewed Th2 response in the respiratory tract during RSV LRTI." (PMID 32357557, 2020). "Variant alleles of TLR2 and TLR4 genes also influenced the susceptibility to adverse effects of traffic-related air pollution on childhood asthma." (PMID 32411804, 2020). "For this study, we chose to explore TLR4 polymorphism rs4986790 because it has been well studied in European populations and there is evidence for its role in respiratory infections and asthma." (PMID 32650475, 2020). "Once again, these features were absent in RAGE/TLR4 deficient mice, suggesting that TLR4 plays an important role in the development of the observed asthma phenotype." (PMID 28099113, 2017). "At present, any effect of the TLR2 and TLR4 gene polymorphisms on asthma is still largely undetermined." (PMID 28262750, 2017). "For instance, sequence variants in the TLR4 gene can affect the responsiveness to LPS, and thereby influence the prevalence of asthma in a population." (PMID 28056766, 2017). "Other TLR2 SNPs have been associated with allergic asthma and TLR4 SNPs (Asp299Gly and T399I) with asthma pathogenesis in a German population." (PMID 27495363, 2016). "S100A8 and S100A9 are important pathogenic mediators in severe asthma because airway resident cells express TLR4, which binds to S100A8 and S100A9, and because both proteins induce pro-inflammatory responses." (PMID 25973752, 2015). "Although TLR4 signaling acts as an anti-inflammatory mechanism in acute lung inflammation induced by hyaluronan, recent reports have demonstrated the importance of TLR4 in HDM-mediated asthma and we reported the association of TLR4 and DP in allergic rhinitis." (PMID 25973752, 2015). "TLR2 and TLR4 are the most relevant to the onset of asthma and to the inflammatory responses underlying asthmatic exacerbations." (PMID 26617525, 2015). "In the present study, we investigated the effects of genetic variants of the CD14(C-159 T) and TLR4 (Asp299Gly and Thr399Ile) polymorphisms on adult asthma phenotypes specifically the severity of disease, total IgE concentrations and eosinophil counts." (PMID 24524443, 2014). "Individuals with the Asp299Gly TLR4 polymorphism were shown to have decreased IL-12 and IL-10 levels produced by mononuclear cells stimulated with LPS and a four-fold higher risk of asthma." (PMID 24524443, 2014). "We aimed to investigate the effects of genetic variants of CD14 (−) and TLR4 (Asp299Gly, Thr399Ile) genes on asthma phenotypes in adults with asthma." (PMID 24524443, 2014). "This study is important because it is the first to evaluate together with the effects of both CD14 and TLR4 genetic variants on disease in adult patients with asthma in Turkey." (PMID 24524443, 2014). "TLR4 is by far the most studied of all TLRs in relation to asthma in children, but only some studies showed an association." (PMID 23496969, 2013). "Polymorphism rs10759931 in TLR4 showed an interaction between childhood asthma symptoms and air pollutant levels." (PMID 23496969, 2013). "Polymorphisms in the endotoxin-mediated TLR4 pathway genes have been associated with asthma and atopy." (PMID 22151743, 2011). "Furthermore, the study lacked an objective marker of microbial exposure, such as endotoxin levels, which limits the ability to fully assess the relationship between TLR4 SNPs, microbial exposure, and asthma risk." (PMID 40761635, 2025). "Using residential living environments (rural vs. urban) as a proxy for microbial exposure, we hypothesize that TLR4 polymorphisms (Asp299Gly and Thr399Ile) may modulate asthma risk differently depending on the living environment." (PMID 40761635, 2025). "Additionally, polymorphisms in the TLR4 gene are significantly correlated with an elevated risk of asthma." (PMID 40672946, 2025).